SIAH2 (siah E3 ubiquitin protein ligase 2)
Diseases named in the same sentence as SIAH2 in open-access papers (continued):
Sharing a sentence is not in itself a finding about the gene and the disease.
pulmonary hypertension (1 paper, 2024). Increased pressure within the pulmonary circulation due to lung or heart disorder. "Vitamin K3, a specific inhibitor of SIAH2, was reported to ameliorate pulmonary hypertension and tumor resistance by inhibiting SIAH2." (PMID 38459604, 2024).
Right ventricular hypertrophy (1 paper, 2023). In this case the right ventricle is more muscular than normal, causing a characteristic boot-shaped (coeur-en-sabot) appearance as seen on anterior- posterior chest x-rays. "Furthermore, GLY, 4-PBA and VK3 administration attenuated the increases of RVSP, mPAP and RV/(LV+S), right ventricular hypertrophy, and pulmonary vascular remodeling by targeting on PERK/ATF4/SIAH2/HIPK2 pathway in PAH rats." (PMID 37268944, 2023).
skin melanoma (1 paper, 2020). "The clinical relevance of our findings was assessed by monitoring changes in Siah2 expression in the TCGA skin melanoma cohort (TCGA_SKCM)." (PMID 31911617, 2020).
squamous cell carcinoma (1 paper, 2014). A carcinoma arising from squamous epithelial cells. "A difference between squamous cell carcinomas (SCC) and adenocarcinomas (ADC) reached statistical significance, with SCC being more frequently positive for SIAH2 (P=0.001)." (PMID 24833526, 2014).
Stroke (1 paper, 2017). Sudden impairment of blood flow to a part of the brain due to occlusion or rupture of an artery to the brain. "All together, we have demonstrated a hitherto unappreciated functional antagonism between Siah2 and drebrin that suggests regulation of drebrin E-mediated cytoskeletal interactions is a novel mechanism for controlling the onset of two-stroke motility and IGL-directed migration in maturing CGNs." (PMID 28230156, 2017).
uveitis (1 paper, 2025). An inflammatory process affecting a part of or the entire uvea. "Machine learning identified IFN-associated genes as robust predictors, while linear discriminant analysis pinpointed CCR2, CD180, GAPT, and PTGS2 as key risk factors in isolated uveitis and CA1, SIAH2, and PGS in systemic disease-associated uveitis." (PMID 40270958, 2025).
tumor (52 papers, 2011 to 2026). "METTL14 stimulates the expression of the tumour development and progression-associated protein seven in absentia homologue 2 (Siah2)." (PMID 40356909, 2025). "Only DEFB1 was up-regulated in the tumor group; in contrast, SIAH2 and SYT1 were down-regulated in the low-risk group (Wilcoxon test, P > 0.05)." (PMID 38393698, 2024). "The results showed that both tumor volume and tumor weight in the nude mice transplanted with SIAH2 knockout cells were decreased, whereas concurrent deficiency of SIAH2 and DBC1 restored tumor growth to a certain extent." (PMID 35913115, 2022). "As a key regulator of hypoxia responses in normal and cancer cells, SIAH2 is positively correlated with metastasis progression that promotes tumor-associated macrophage recruitment in the hypoxic tumor microenvironment." (PMID 35313831, 2022). "Taken together, these data suggested that Siah2 deficiency in tumor cells enhanced T-cell–mediated antitumor activity and vice versa." (PMID 35154166, 2022). "Siah2-dependent effects on p27 are likely manifested following the stress accompanying immune cell stimulation (via T cell receptor signaling) or harsh tumor environment, conditions implicated for Siah2 activities." (PMID 31911617, 2020). "Fatty acid levels were reduced in SIAH2-knockdown cells when cultured under hypoxia, which was further validated in SIAH2-deficient xenograft tumor tissues by weakened Oil Red staining." (PMID 30833558, 2019). "Moreover, SIAH2 colocalizes with a subset of the stromal tumor-associated macrophages (IBA1) in the more fibrotic DDLPS." (PMID 35313831, 2022). "The decreased frequency of tumor-infiltrating Tregs seen in Siah2−/− mice could be attributed to alterations in the cell cycle, a possibility consistent with reports that Siah2 loss in vitro decreases cell proliferation." (PMID 31911617, 2020). "Although SIAH2 was proposed as a tumor promoter that mediates the K63-linked ubiquitination and nuclear translocation of AR-FL 31, its role in the regulation of AR-V7 or other AR-Vs and the progression of CRPC remains largely unknown." (PMID 32206096, 2020). "We also show changes in DCs, where Siah2 loss increased expression of the IFNγ-induced chemokine Cxcl9, which recruits effector T cells to a tumor site, and concomitantly decreased expression of Ccl17 and Ccl22, chemokines that contribute to recruitment of Tregs to tumors." (PMID 31911617, 2020). "Alterations or changes in the expression of those kinases able to phosphorylate SIAH2 in tumor cells could be one of the underlying mechanisms responsible of this difference between mRNA and protein expression." (PMID 26580787, 2015). "High levels of SIAH2 may be partly responsible for the enhanced hypoxic drive that underlies this tumor type, which is chemotherapy- and radiotherapy-resistant." (PMID 21306611, 2011). "Functional studies across multiple CRC cell lines showed that SIAH2 silencing suppressed proliferation, clonogenic growth, tumor sphere formation, and cell-cycle progression, whereas SIAH2 overexpression exerted opposite effects." (PMID 41596707, 2026). "A recent study has shown that the SIAH2–nuclear respiratory factor 1 (NRF1) axis reshapes the TME by modulating several processes such as tumor mitochondrial function, TAM polarization, and cell death." (PMID 39748782, 2025). "When the tumor microenvironment is in hypoxia, the hypoxia‐induced E3 ligase SIAH2 degrades NRF1, which downregulates the expression of nuclear‐encoded mitochondrial genes, leading to an enhanced pro‐tumor immune response." (PMID 39748782, 2025).
tumor (continued). "Our analysis of differential expression indicated that ANO6 and IL33 were markedly downregulated in cancerous tissues relative to normal ones, whereas SIAH2 showed elevated expression in tumor samples." (PMID 39911848, 2025). "A previous study suggested that SIAH2 enhances the anti-inflammatory and proliferative abilities of cells and contributes to tumor microenvironment remodeling." (PMID 41183121, 2025). "SIAH2 can mediate ubiquitination and degradation of substrates and regulate multiple signaling pathways in response to hypoxic stress, thereby promoting tumor occurrence and progression." (PMID 39911848, 2025). "The suppression of Siah2 hinders the proliferation and cytotoxic capabilities of T cells, as it sustains the expression of PD-L1 on tumour cells." (PMID 40356909, 2025). "Specifically, BRD4, FLT3, and SIAH2 were upregulated in tumor tissues, whereas CS and PIK3CA were downregulated." (PMID 40696656, 2025). "Methylation analysis showed that the beta value of SIAH2 was higher in the tumor group than in the normal group, and DEFB1 was the opposite." (PMID 38393698, 2024). "SIAH2 encodes a RING-type ubiquitin E3 ligase, which has been shown to have both oncogenic and tumor-suppressive roles in tumorigenesis and metastasis in several cancers." (PMID 38773237, 2024). "(F–H) Tumor images (F), tumor growth curves (G), and tumor weight (H) from mice subcutaneously injected with SIAH2 knockout or SIAH2/CCAR2 double-knockout MDA-MB-231 cells." (PMID 35913115, 2022). "IHC detection of Siah2 and PD-L1 indicated that SD specimens displayed low Siah2 expression and PD-L1–positive expression on CCA tumor cells, and PD specimens displayed high Siah2 expression and PD-L1-negative expression." (PMID 35154166, 2022). "We also observed that in vitro and in vivo Siah2 knockdown inhibited T cells expansion and cytotoxicity by sustaining tumor cell PD-L1 expression." (PMID 35154166, 2022). "Numerous studies have determined that Siah2 exerts its biological function, depending on the tumor development stage." (PMID 35154166, 2022). "Analyzing the data from TCGA, we found that SIAH2 was positively correlated with tumor stage and number of lymph nodes, indicative of tumor malignancy." (PMID 35913115, 2022). "(J) EdU proliferation analysis of different tumor cells isolated from SIAH2 knockout or SIAH2/CCAR2 double-knockout xenografts." (PMID 35913115, 2022). "Human tissue microarray analysis further revealed that the SIAH2/DBC1 axis was responsible for regulating tumor progression under hypoxic stress." (PMID 35913115, 2022). "By applying CD34+ humanized NCG mice model and PCCA cell model analysis, we further found that Siah2 enhanced in vivo antitumor T-cell immunity in a PD-L1–dependent manner, unveiling a complex role of Siah2 in the tumor-immune microenvironment." (PMID 35154166, 2022). "The difference of cell susceptibility to T-cell killing between PCCA#2-LV-NC and PCCA#2-LV-Siah2 was reversed by blocking PD-L1 with pembrolizumab, indicating that PD-L1 is required for Siah2-mediated tumor resistance to T-cell antitumor activity." (PMID 35154166, 2022). "SIAH2’s roles in adipogenesis and tumor development suggest that factors in adipocyte precursor cells controlling PPARG2 mRNA expression are potentially dysregulated in the development of DDLPS." (PMID 35313831, 2022). "Alternatively, SIAH2 is expressed in a substantial number of stromal cells present in the DDLPS, including tumor-associated macrophage that are abundant in DDLPS." (PMID 35313831, 2022). "Human tissue microarray analysis further revealed that the SIAH2/DBC1 axis was responsible for tumor progression under hypoxic stress." (PMID 35913115, 2022). "In the present study, we demonstrated that tumor-intrinsic Siah2-PD-L1 axis inhibited T cell–mediated cytotoxicity." (PMID 35154166, 2022). "SIAH2 has been defined as a central regulator of tumorigenesis and tumor progression by mediating ubiquitination of diverse cellular substrates." (PMID 35582023, 2021).
tumor (continued). "Fluorescence-activated cell sorting (FACS) analysis of tumor cell populations revealed that among Foxp3+ cells, 40% were Siah2−/− and 60% were Siah2 WT." (PMID 31911617, 2020). "Increasing the number of tumor cells inoculated (from 4 × 105 to 1 × 106) abrogated the tumor rejection phenotype in Siah2−/− mice, suggesting that tumor burden is a critical determinant of effective Siah2-dependent immune cell function." (PMID 31911617, 2020). "Our ability to rescue, in part, Treg recruitment and tumor growth in Siah2−/− mice subjected to treatment with neutralizing antibodies to Ccl17 and Ccl22 further illustrates the independent pathways by which Siah2 controls tumor growth." (PMID 31911617, 2020). "Here, we identify a role for the ubiquitin ligase Siah2 in control of intratumoral Treg proliferation and tumor infiltration." (PMID 31911617, 2020). "To further assess Siah2-dependent changes in tumor-infiltrating immune cell populations, we carried out single-cell RNAseq analysis of CD45+ cells from YUMMER1.7 tumors grown in WT or Siah2−/− mice." (PMID 31911617, 2020). "Another function of Siah2 is the degradation of tumor‐suppressors, thus contributing to cell transformation." (PMID 26832397, 2016). "A role of Siah2 in tumor formation and metastasis has already been established in genetically engineered mouse models." (PMID 26832397, 2016). "These samples were selected to represent a wide range of SIAH2 mRNA differential expression between tumor and normal tissues." (PMID 26580787, 2015). "Changes in expression of SIAH2 in tumor samples compared to normal lung samples were expressed as a fold-change." (PMID 26580787, 2015). "The human Siah1 and Siah2 isoforms share high sequence similarity but possess contrary roles in cancer, with Siah1 more often acting as a tumor suppressor while Siah2 functions as a proto-oncogene." (PMID 25202994, 2014). "SIAH2 is known to regulate the immune system and control anti-tumor immunity and is also believed to promote the production of neovascularization and may affect keratinocytes’ migrating through partial Epithelial-Mesenchymal Transition." (PMID 41183121, 2025). "Second, hypoxic conditions within the tumor microenvironment may lead to the ubiquitin-mediated degradation of DBC1 via SIAH2, thereby affecting its stability and expression in different lesions." (PMID 40692869, 2025). "Moreover, an examination of samples from patients subjected to anti-PD-1 immunotherapy indicated that tumours exhibiting reduced Siah2 levels responded more positively to the treatment." (PMID 40356909, 2025). "Upon the depletion of Siah2, it increased the protein stability of PD-L1 and then inhibited T cells expansion and T-cell–mediated anti-tumor activity in CCA cells, indicating the clinical potential of the METTL14-Siah2-PD-L1–regulating axis for CCA immunotherapy." (PMID 36960074, 2023). "SIAH2 knockout inhibited tumor cell proliferation and migration, which could be rescued by double knockout of SIAH2/CCAR2." (PMID 35913115, 2022). "However, in primary tumor specimens, SIAH2 mRNA was consistently upregulated in DDLPS compared to WDLPS when assayed by fluorescence in situ hybridization or real-time PCR." (PMID 35313831, 2022). "Tumor heterogeneity in the tissues may account for the variability in SIAH2 protein levels, but we also noted that SIAH2 mRNA is consistently expressed at higher levels in the DDLPS tissues compared to normal retroperitoneal adipose tissue or WDLPS tissues." (PMID 35313831, 2022). "(C) Relative expression level of SIAH2 in tumor stage (stages 1, 2, 3, 4, or 5) from BRCA patients." (PMID 35913115, 2022). "For deeper understanding of Siah2 role in ICC tumor immune microenvironment, we used CD34+ humanized NCG mice models, which have the same composition of immune cell subsets, especially regarding myeloid cells, which are considered to be a better preclinical model." (PMID 35154166, 2022).
tumor (continued). "Importantly, treatment with the specific Siah2 inhibitor, vitamin K3 (Vit K3), delayed LNCaP tumor progression to castration resistance in LNCaP tumors." (PMID 33937036, 2021). "Additionally, Siah2 is required for CRPC tumor growth in mice, whereas Siah2 deletion increases the castration sensitivity of TRAMP mice." (PMID 33937036, 2021). "Along this line of reasoning, SIAH2 may contribute to the tumor promoting functions of these kinases by activating the HIF-1 pathway and the hypoxic response." (PMID 33842469, 2021). "While these activities are associated with immune cell function, direct evidence for Siah2 regulation of anti-tumor immunity has been lacking." (PMID 31911617, 2020). "Thus, among the diverse T cell populations, the intratumoral Tregs are the most sensitive to Siah2 deletion, reflected by the highest degree of G1 block among tumor-infiltrated immune cell populations." (PMID 31911617, 2020). "Here, using a genetic mouse model of global Siah2 deletion, we show that Siah2 functions in intratumoral recruitment and cell cycle control of T cells with the most notable impact on T regulatory cells (Tregs), supporting a function in anti-tumor immunity." (PMID 31911617, 2020). "Our results also identified that mitochondria are spatially organized in response to tumor hypoxia through the degradation of NRF1 by the hypoxia-induced E3 ligase SIAH2, resulting in mitochondrial heterogeneity which consequentially potentiates metabolic heterogeneity." (PMID 30833558, 2019). "Given the importance of Siah2 in the regulation of mitochondrial metabolism and its tumor‐promoting role, it is worth mentioning that the NCoR1/HDAC3 repressor complex also controls cell proliferation via its role in cell cycle regulation and DNA repair pathways." (PMID 26832397, 2016). "We show that LIM domain protein Zyxin, as a scaffold protein, in response to hypoxia and TGF-β stimuli, forms a ternary complex with Siah2 and Lats2, thus stabilizes their interaction, and facilitates deactivation of the Hippo signalling, thereby promoting tumour progression." (PMID 27030211, 2016). "Our results support this hypothesis, highlighting that the observed increase in SIAH2 expression depends on the histological tumor grade." (PMID 26580787, 2015). "Thus Siah2 plays an important role in hypoxia dependent signaling, and this is likely to contribute to its tumor promoting activity." (PMID 25202994, 2014). "It is tempting to speculate that an increased expression of SIAH2 during malignant progression may inactivate tumor barriers." (PMID 24833526, 2014). "In addition, in silico modeling has predicted that the tumor suppressors SIAH2 and ST7L are also potential targets of miR-146a." (PMID 24302991, 2013). "Therefore, we examined whether SIAH2-mediated DBC1 ubiquitination was responsible for tumor progression." (PMID 35913115, 2022). "Here, we demonstrate that via its regulation of p27 stability in stimulated T cells, Siah2 controls T cell proliferation, which affects the availability of intratumoral Treg, but not effector T cells, thereby enhancing effectiveness of the cytotoxic T cell and overall anti-tumor immunity." (PMID 31911617, 2020). "Hence, we believe that regulation of NRF1 expression via SIAH2 by oxygen tension is a switch for a series of intrinsic and extrinsic cellular reactions during tumor progression, which may be of great importance for tumor maintenance." (PMID 30833558, 2019). "Thus, inhibiting SIAH2 may also enhance EAF2 tumor suppressive activity, in addition to inhibiting castration-resistant AR activation." (PMID 27058417, 2016). "When comparing the tumor tissues and the normal tissues, the expression of BRD4, EMC2, FLT3, and SIAH2 was upregulated in the tumor tissues." (PMID 40696656, 2025).